ALDH1L1 (aldehyde dehydrogenase 1 family member L1)
Diseases named in the same sentence as ALDH1L1 in open-access papers (continued):
Sharing a sentence is not in itself a finding about the gene and the disease.
cancer (continued). "Analysis of ALDH1L1 expression by immunohistochemical staining showed that NSCLC cancer patients showed a higher expression level than normal control showed." (PMID 32481524, 2020). "ALDH1L1, on the other hand, is silent in malignant tumors, and its re-expression in cancer cells elicits anti-proliferative effects." (PMID 32271159, 2020). "In agreement with such function, ALDH1L1 is strongly and ubiquitously downregulated in many human cancers through the promoter methylation." (PMID 33168096, 2020). "While the phenomenon of ALDH1L1 silencing/down-regulation in cancer is now well recognized, the effects of exonic SNPs on the protein function in tumorigenesis and tumor progression are not clear." (PMID 31737034, 2019). "Analysis of gene expression profiles across 33 human cancer types using The Cancer Genome Atlas (TCGA) data indicated that ALDH1L1 is more strongly down-regulated in late-stage cancers." (PMID 31737034, 2019). "Numerous studies have established that ALDH1L1 is often silenced or strongly down-regulated in cancers." (PMID 31737034, 2019). "SNPs in ALDH1L1 are common but their effect on metabolism and the etiology of cancer disease is not well understood." (PMID 31737034, 2019). "In line with its antiproliferative function, ALDH1L1 is often silenced or strongly down-regulated in cancer cell lines and malignant tumors [reviewed in]." (PMID 31737034, 2019). "Several studies have established that the silencing of ALDH1L1 in human cancers is driven by gene methylation." (PMID 31737034, 2019). "In human cancers and cell lines derived from malignant tumors, the ALDH1L1 gene is commonly silenced through the promoter methylation." (PMID 29979702, 2018). "We have employed two targets of ALDH1L1 and mitochondrial OxPhos complex I for a combinational inhibition to achieve cancer specific ATP depletion." (PMID 30356107, 2018). "NSCLC cancer cells adopted a special source of electron for ATP synthesis through OxPhos from cytosolic NADH produced by ALDH1L1 in the one carbon pathway 7–9." (PMID 30356107, 2018). "Tissue-specific expression of ALDH1L1 and its strong suppression in certain cancer types suggest that the gene is tightly regulated." (PMID 29868117, 2018). "ALDH1L1 is usually underexpressed in cancer cells, as its overexpression would deplete the cytosolic 10-formyl-THF used for the synthesis of nucleotides." (PMID 29740540, 2018). "Similar drop in ALDH1L1 expression had been observed in the majority of other malignant tumors tested so far." (PMID 29868117, 2018). "At the same time, high hypermethylation score of a CpG site was not necessarily resulted in strong negative correlation between hypermethylation of this site in cancer and relative expression level of ALDH1L1 gene." (PMID 29868117, 2018). "It has been also demonstrated that the expression of ALDH1L1 is ubiquitously lost in cancer cell lines." (PMID 29979702, 2018). "Previously, we reported that the common mechanism of ALDH1L1 down-regulation in cancer cells is its promoter methylation." (PMID 29979702, 2018). "Future investigations regarding the critical role of ALDH1L1 in cancer cell survival and induction of folate stress will provide important insights into the malignant process." (PMID 28792511, 2017). "The expression level of ALDH1L1 was significantly higher (P < 0.001, marked by *) in cancer tissues (cancer) than normal lung type I and II pneumocytes (normal)." (PMID 27384481, 2016). "ALDH1L1 regulates the conversion of serine to glycine, and these two amino acids have been shown to play key roles in oncogenesis, including the regulation of cancer cell proliferation." (PMID 39728477, 2024). "ALDH1L1 is frequently and ubiquitously downregulated in human cancers due to promoter methylation." (PMID 39728477, 2024). "Future studies could explore the correlation of these pathways with ALDH1L1-related diseases, such as cancer, and assess their implications for developing novel treatments." (PMID 39728477, 2024).
cancer (continued). "In addition, to high extent, the ALDH1L1 gene is suppressed in high‐grade malignant tumors, when compared to low‐grade tumors." (PMID 36336972, 2023). "The best illustration of ALDH1L1 regulation is its silence in malignant tumors." (PMID 36336972, 2023). "In this regard, ALDH1L1 acts similar to anti‐FA drug against cancer progression." (PMID 36336972, 2023). "The most striking example is the methylation-driven silencing of the ALDH1L1 gene in human cancers." (PMID 35629957, 2022). "Overall, though our study was exploratory, it supports the hypothesis that downregulation of ALDH1L1 in cancer cells strongly affects cellular metabolism, which might provide proliferative and migratory advantage." (PMID 36500483, 2022). "Question 2: Is ALDH1L1 protein expression high or low in cancer?" (PMID 34066916, 2021). "Question 3: Is ALDH1L1 expression high or low in cancer by analysis of public informatics?" (PMID 34066916, 2021). "Cancers often loose the enzyme of folate metabolism ALDH1L1." (PMID 34203215, 2021). "Numerous reports demonstrating that the major folate enzyme ALDH1L1 is strongly and ubiquitously downregulated in human cancers have led to a hypothesis that the protein could be a putative tumor suppressor." (PMID 34203215, 2021). "Is ALDH1L1 expression high or low in cancer by analysis of public informatics?" (PMID 34066916, 2021). "In addition, Aldh1l1, which is known to be downregulated in cancer through promoter methylation, is upregulated in our IBD model and exhibits two regions with reduced cytosine hydroxymethylation." (PMID 33396408, 2020). "Furthermore, the protective effect of ALDH1L1 on THF degradation has been recently observed in cancer cells." (PMID 31737034, 2019). "On the whole, these data indicate that promoter hypermethylation might be a common mechanism of ALDH1L1 downregulation in human cancers." (PMID 29868117, 2018). "Currently, it cannot be said with certainty whether ALDH1L1 is a bona fide tumor suppressor gene or a mere “passenger” which promoter is frequently hypermethylated in cancer." (PMID 29868117, 2018). "ALDH1L1 and WIF1 have been shown to be ubiquitously downregulated in cancers, and their downregulation was associated with poor clinical outcomes in cancer." (PMID 28427185, 2017). "ALDH1L1 could inhibit cancer cell motility via dephosphorylation of cofilin by PP1 and PP2A in folate-specific manner." (PMID 27015121, 2016). "Our data contribute to the tumor suppressor role of ALDH1L1 in carcinomas." (PMID 24977159, 2014). "Thus, the overall relationship between GNMT and cancer is reminiscent of another folate regulatory enzyme, ALDH1L1, which is also silenced in tumors and exerts strong antiproliferative effects in cell culture models." (PMID 23936142, 2013). "Also, re-expression of ALDH1L1 in cancers cells has been shown to reduce proliferation and induce apoptosis, suggesting that ALDH1L1 may be a putative tumor suppressor." (PMID 39728477, 2024). "Overall, ALDH1L1 could be a candidate tumor suppressor for aggressive cancers." (PMID 36694633, 2023). "Thus, the possibility cannot be excluded that the decreased GSH in Aldh1l1 KO mice is an indication of enhanced ROS removal, which could be beneficial for cancer cell survival." (PMID 34203215, 2021). "However, the prognostic role of ALDH1L1 may be cancer‐type‐specific." (PMID 36694633, 2023). "Aldehyde dehydrogenase 1 family member L1 (ALDH1L1) is an important enzyme involved in folate metabolism, a candidate tumour suppressor and a potential marker for aggressive cancer." (PMID 35597868, 2022). "ALDH1L1 activates JNK1 and JNK2 and increases the level of a full-length Bid in cancer cells as a pro-apoptotic response." (PMID 34572930, 2021). "Several isoforms of the ALDH1 family (ALDH1A1, ALDH1A2, ALDH1A3, ALDH1B1, ALDH1L1, and ALDH1L2) are used as cancer stem cell markers in a variety of cancers." (PMID 34680942, 2021).
cancer (continued). "Therefore, the knockdown of KRAS showed stronger effect of ALDH1L1 expression compared to over expression of KRAS in cancer cells, because all transcription factors, as well as downstream signaling molecules, may be required to increase the transcription activity of ALDH1L1." (PMID 32481524, 2020). "Among the enzymes that catalyze the reactions coupled with the production of NADPH, THF dehydrogenases (cytosolic ALDH1L1 and mitochondrial ALDH1L2) and MTHF-dehydrogenases (mitochondria MTHFD2L and cytosolic MTHFD1) are involved in cancer." (PMID 29740540, 2018). "We also found a number of genes whose expression follows this pattern: high-grade cancers < low-grade cancers < normal tissue, such as ALDH1L1, WIF1, ACSL1, FOS, and ABLIM1 in at least four cancer types." (PMID 28427185, 2017). "We have recently found a cancer cell line, RT4, expressing high levels of ALDH1L1." (PMID 36500483, 2022). "As well, cancer cell lines do not express ALDH1L1 and present strong hypermethylation of the ALDH1L1 promoter region." (PMID 36500483, 2022). "ALDH1L1 (cytosolic 10-formyltetrahydrofolate dehydrogenase), an enzyme of folate metabolism expressed in many tissues, is ubiquitously downregulated in cancers and is not expressed in cancer cell lines." (PMID 36500483, 2022). "Similar to ALDH1L1, GNMT is highly expressed in the liver (comprising up to 3% of the total cytosolic protein in hepatocytes) but ubiquitously downregulated in many cancers, including HCC." (PMID 34203215, 2021). "ALDH1L1 is not expressed in the vast majority of cancer cell lines because of extensive methylation of the ALDH1L1 promoter, the mechanism also responsible for the silencing of this gene in malignant human tumors." (PMID 34203215, 2021). "The ALDH1L1 gene is also under-expressed in human cancers compared to respective normal tissues, with certain malignant tumors completely lacking the ALDH1L1 protein." (PMID 29979702, 2018). "In contrast to cancer cells, mouse cell lines NIH3T3 and AML12 do express the ALDH1L1 protein." (PMID 29979702, 2018). "These genes include tumor suppressors or candidates (VHL, CTDSPL, LRRC3B, ALDH1L1, and EPHB1) and genes that were not previously considered as cancer-associated (e.g., LRRN1, GORASP1, FGD5, and PLCL2)." (PMID 24977159, 2014). "The expression of ALDH1L1 at both mRNA and protein levels is usually absent in malignant tumors." (PMID 36336972, 2023). "However, our previous studies of numerous human cancer cell lines did not identify any cancer cells expressing ALDH1L1." (PMID 36500483, 2022). "The expression of ALDH1L1 in two cell lines of non-cancerous origin, HEK293 and NIH3T3, was reported, indicating that the antiproliferative effect of the enzyme is likely linked to a cancer metabotype." (PMID 36500483, 2022). "It is not clear whether the antiproliferative effect of ALDH1L1 is mostly limited to cancer cells or if the enzyme also participates in regulating the proliferation of normal cells." (PMID 29979702, 2018). "This hypothesis is further supported by the finding that ALDH1L1 is reversibly downregulated in the S-phase of the cell cycle in NIH3T3 cells, though through a different mechanism (i.e., proteasomal degradation in NIH3T3 cells versus promoter methylation in cancer cells)." (PMID 34203215, 2021). "Not surprisingly, in our results, the ALDH1L1 was indicated as a potential poor prognostic biomarker for GC, and that the promoter methylation may be a major mechanism controlling ALDH1L1 levels in human cancers." (PMID 27015121, 2016). "In this regard, it is not clear why, in contrast to most other cancer cell lines, RT4 cells express ALDH1L1 to a significant level." (PMID 36500483, 2022). "In contrast to ALDH1L1, GNMT, another folate-related enzyme commonly silenced in human cancers, was not expressed in NIH3T3 cells." (PMID 29979702, 2018).
cancer (continued). "Intriguingly, the expression of SHMT1, MTHFD1, and ALDH1L1 had no influence on the survival rate of patients with CRC and LA, suggesting it is not the folate metabolism per se but the THF cycle in the mitochondria that confers poor prognosis in cancers." (PMID 29321536, 2018).
tumor (38 papers, 2009 to 2026). "Additional research is required to further explore the correlation between specific alterations in these pathways and tumor growth, as well as to identify potential dietary interventions to mitigate the detrimental effects of ALDH1L1 loss." (PMID 39728477, 2024). "Here, we provided evidence that low ALDH1L1 expression in OSCC is associated with more malignant tumor phenotypes and poor survival." (PMID 36336972, 2023). "We found that the expression level of ALDH1L1 was significantly reduced in OSCC, and the downregulation of ALDH1L1 expression in tumor tissues was associated with poor prognosis of patients." (PMID 36336972, 2023). "In our study, in agreement with the tumor-promoting effect of the ALDH1L1 loss, both NF-κB and IL-6 were strongly elevated in Aldh1l1 KO livers compared to WT livers." (PMID 34203215, 2021). "Accordingly, in our study, a stronger decrease of these metabolites in DEN-treated Aldh1l1 KO versus DEN-treated WT mice is in agreement with the tumor-promoting effect of the Aldh1l1 loss." (PMID 34203215, 2021). "We proposed that such loss is advantageous for the malignant tumor growth and tested this hypothesis in mice proficient or deficient (gene knockout) in ALDH1L1 expression." (PMID 34203215, 2021). "In the present study, we investigated whether the loss of ALDH1L1 has an effect on tumor initiation and progression in a DEN model of liver carcinogenesis." (PMID 34203215, 2021). "We proposed that ALDH1L1 loss promotes malignant tumor growth." (PMID 34203215, 2021). "However, if ALDH1L1 functions as a tumor suppressor, it could be expected that its loss enhances tumorigenesis." (PMID 34203215, 2021). "Stemness-associated genes such as GDF15, ALDH1L1, GPC3, AFP, EPCAM, CD44, and CD24 were predominantly expressed in tumor cells, with varying levels across other cell types including CAFs, TECs, and TAMs." (PMID 41493679, 2026). "ALDH1L1 silencing has been shown to confer a metabolic advantage for tumor progression as it supports cell proliferation." (PMID 39957677, 2025). "To illustrate these phenomena at the molecular level, we have shown that mesothelial cells co-cultured with tumor cells significantly enhanced the well-known and well-defined stemness markers Nanog, Oct3/4, Sox2, and ALDH1L1 in OvCa cells." (PMID 38575576, 2024). "Our results showed that tumor volumes as well as weights and tumor cell proliferation (as assessed by Ki‐67 index) were increased in the mice injected with ALDH1L1‐knockdown CAL‐27 cells compared with the control group." (PMID 36336972, 2023). "In this study, we revealed that ALDH1L1 expression was significantly reduced in OSCC, and its downregulation was associated with the malignancy of the tumor and poor prognosis of patients." (PMID 36336972, 2023). "Conversely, ALDH1L1‐overexpressing SCC‐25 cells resulted in formation of significantly small tumor volumes, weights, and suppressed tumor cell proliferation, relative to control group." (PMID 36336972, 2023). "Re‐expression of ALDH1L1 in tumor cells has been shown to lead to drastic anti‐proliferative outcomes, such as cell cycle arrest as well as apoptosis." (PMID 36336972, 2023). "In this study, to understand the role of ALDH1L1 in tumor suppression, we expressed ALDH1L1 in HuH-7 cells, which have reduced ALDH1L1 expression, and compared the effects of ALDH1L1 expression in HuH-7 cells." (PMID 37596270, 2023). "In previous cell phenotypic experiments, we show that ALDH1L1 can promote the arrest of tumor cells in G0/G1 and G2/M phases." (PMID 36336972, 2023). "We demonstrated that ALDH1L1 suppresses tumor proliferation, survival, cell cycle progression, and invasion via inhibiting PI3K/Akt/Rb signaling pathway." (PMID 36336972, 2023). "In fact, ALDH1L1 participates in a variety of biological pathways related to cellular proliferation in tumor cells." (PMID 36336972, 2023).